CTSB (cathepsin B)
Diseases named in the same sentence as CTSB in open-access papers (continued):
Sharing a sentence is not in itself a finding about the gene and the disease.
Hypertension (11 papers, 2019 to 2025). The presence of chronic increased pressure in the systemic arterial system. "Low cathepsin B expression was associated with reduced expression and activity of the epithelial sodium channel (ENaC), sodium retention, and thus control of hypertension." (PMID 36830842, 2023). "As an underlying mechanism cathepsin B induced αENaC processing leading to augmented channel activity and hypertension was identified." (PMID 31368174, 2019). "Total renal volume, cortical volume, and urinary activity of N-acetyl-β-d-glucosaminidase and cathepsin B may be suggested as indicators for the early recognition of GDM neonates at long-term risk of hypertension and kidney disease." (PMID 30925803, 2019). "In the collecting duct, CTSB is also considered an important participant in sodium retention and hypertension." (PMID 40129990, 2025). "Cathepsins, particularly CTSB and CTSS, have been implicated in the pathogenesis of hypertension by promoting vascular smooth muscle proliferation, extracellular matrix degradation, cardiomyocyte hypertrophy, and the activation of the RAAS." (PMID 40710492, 2025). "In conclusion, the pathogenesis of CTSB in hypertension and related diseases is intricate and involves multiple cells and organs, making it complex and multifaceted." (PMID 39248527, 2024). "While research on CTSB in hypertension has a long history, the specific mechanisms are still unclear." (PMID 39248527, 2024). "Further experimental investigations are required to clarify the pathological mechanisms of CTSB in hypertension and related conditions." (PMID 39248527, 2024). "Renal ENaC activity augmented by cathepsin B was shown to lead to an increase in sodium retention and hypertension in mice with nephrotic syndrome." (PMID 38791000, 2024). "The application of CA‐074Me, a membrane‐permeable inhibitor of CTSB, can effectively prevent hypertension." (PMID 39248527, 2024). "Hypertension was prevented by inhibiting cathepsin B. In conclusion, the identified mechanism involves the cathepsin B-induced processing of αENaC, resulting in heightened channel activity and the development of hypertension." (PMID 38139392, 2023). "Cathepsin B was shown to increase ENaC activity leading to the development of hypertension in nephrotic syndrome." (PMID 34630137, 2021). "Inhibition of cathepsin B influenced the development of hypertension demonstrating its important role in this disease model." (PMID 31368174, 2019). "However, the role of cathepsin B in the pathophysiology of hypertension in the diabetic kidney is incompletely understood." (PMID 36830842, 2023). "As a type of αENaC cleaving enzyme, blockade of CTSB can prevent hypertension." (PMID 37576397, 2023). "Cathepsin B cleaves and activates renal ENaC and contributes to the development of hypertension." (PMID 36830842, 2023). "We identified a novel mechanism by which metformin may alleviate high blood pressure by attenuating cathepsin B levels in the kidney and in EVs to reduce ENaC activity (graphical representation)." (PMID 36830842, 2023). "In addition to being correlated with severity, CTSL was also positively correlated with age and history of hypertension but was negatively correlated with CTSB." (PMID 33774649, 2021). "Cathepsin B was identified as αENaC cleaving enzyme where its blockade prevented hypertension." (PMID 31368174, 2019). "CTSB can cleave α - ENaC and activate ENaC in situ, or it may increase the activity of ENaC by acting on proteins known to regulate the insertion, gating, recycling, or degradation of ENaC, thereby promoting hypertension in patients with nephrotic syndrome." (PMID 40129990, 2025). "The goals of this study were to investigate whether there are changes in EV lipid profiles and investigate the type of cell death in kidney cells, independent of cathepsin B, after streptozotocin-induced type 1 diabetes and hypertension." (PMID 38791000, 2024).
schistosomiasis (10 papers, 2014 to 2023). An infectious disease caused by parasitic trematodes of the genus Schistosoma that colonize human blood vessels and release eggs that can cause granulomatous reactions leading to acute (swimmer's itch or acute schistosomiasis syndrome) or chronic disease. "For instance, vinyl sulfone cysteine protease inhibitor K11777 (a substrate-based inhibitor of the gut-associated cathepsin B1 cysteine protease) showed significant efficacy on schistosomiasis in murine model." (PMID 34327203, 2021). "K11777 is also effective in vitro and in vivo in a number of parasites which all have a central cathepsin B or L linked to pathogenicity including schistosomiasis, amebiasis, Tritrichomonas foetus, Leishmania tropica, hookworm, and Cryptosporidium parvum." (PMID 29565998, 2018). "It has been demonstrated that immunizations with Sm-Cathepsin B alone can significantly decrease parasite burden in a mouse model of schistosomiasis." (PMID 30090103, 2018). "Our results demonstrate how the different Sm-Cathepsin B formulations influence the immune mechanisms involved in parasite killing and protection against schistosomiasis." (PMID 30090103, 2018). "Our past vaccine studies using the candidate Sm-Cathepsin B induced promising protection levels against schistosomiasis in mice whether formulated with Montanide ISA 720 VG or CpG dinucleotides adjuvants." (PMID 30090103, 2018). "Recently, our collaborators have demonstrated the inbuilt adjuvant properties of Sm-cathepsin B. Immunizations with unadjuvanted Sm-cathepsin B could decrease both worm and hepatic egg burdens in a mouse model of schistosomiasis by 66 % and 51 %, respectively, when compared to saline control mice." (PMID 26945988, 2016). "Although both formulations, Sm-Cathepsin B in combination with CpG and with Montanide ISA 720 VG, elicited significant protection in a mouse model of schistosomiasis, the immune responses which they generated differed." (PMID 30090103, 2018). "The present study was designed to investigate the protective potential of a Sm-cathepsin B formulation with the adjuvant Montanide ISA 720 VG (SEPPIC Inc., Fairfield, NJ, USA) in a mouse model of schistosomiasis." (PMID 26945988, 2016). "The results obtained from this study are promising and promote further testing of the vaccine candidate Sm-cathepsin B. In the future, the formulation can potentially be tested in a non-human primate model of schistosomiasis." (PMID 26945988, 2016).
Sepsis (10 papers, 2018 to 2025). Sepsis is defined as life-threatening organ dysfunction caused by a dysregulated host response to infection. "Finally, we selected six DEPs that were closely associated with sepsis: cathepsin B (CatB), vascular endothelial cell adhesion molecule (VCAM-1), neutrophil gelatinase-associated lipoprotein (NGAL), protein S100-A9, prosaposin, and thrombospondin-1 (TSP-1)." (PMID 39049003, 2024). "CTSB was found to contribute to the pathogenesis of sepsis-induced acute kidney injury, and the CTSB inhibitor CA074 was shown to alleviate this condition." (PMID 40152606, 2025). "In this research, it was discovered that CTSB was elevated in sepsis mice, and silence of CTSB further boosted the protection of Cur." (PMID 35992541, 2022). "The experiments uncover a brand-new latent mechanism of Cur in sepsis, that is, Cur elevated miR-183-5p via CTSB-mediated PI3K/AKT pathway to strengthen the LPS-stimulated immune function of sepsis mice." (PMID 35992541, 2022). "Subsequently, detection of CTSB in sepsis mice was implemented, illuminating that CTSB was augmented in sepsis mice, while Cur treatment was available to constrain CTSB." (PMID 35992541, 2022). "In this study, the AKI model of sepsis in mice was established, and the protein spectrum detection and bioinformatics analysis of kidney tissues showed that lysosomes and CTSB exacerbate acute kidney injury in sepsis." (PMID 36713420, 2022). "In this study, the influence of Cur on the inflammatory response and immune function of sepsis mice via augment of miR-183-5p and Cathepsin B (CTSB)-mediated phosphatidylinositol 3-kinase (PI3K)/AKT pathway was explored." (PMID 35992541, 2022). "The data above suggested that lysosomes and CTSB were involved in S-AKI, and LMP and CTSB leakage were associated with kidney injury in sepsis." (PMID 36713420, 2022). "Cur was available to accelerate miR-183-5p, which negatively modulated CTSB and Cur-mediated PI3K/AKT pathway via the miR-183-5p/CTSB axis to restrain inflammation of sepsis mice and enhance its immune function." (PMID 35992541, 2022). "Inhibition of CTSB might be a new therapeutic strategy to alleviate sepsis-induced acute kidney injury." (PMID 36713420, 2022). "Cathepsin B (CatB), vascular cell adhesion protein 1 (VCAM-1), neutrophil gelatinase-associated lipocalin (NGAL), protein S100-A9, prosaposin, and thrombospondin-1 levels were significantly increased in the patients with sepsis compared with those of the controls (p < 0.001)." (PMID 39049003, 2024). "In the present study, levels of the LAMP-2 and Rab7 proteins were significantly decreased in mice with sepsis-induced liver injury, but levels of the cathepsin B protein were not changed." (PMID 30154452, 2018).
dementia (9 papers, 2012 to 2025). Loss of intellectual abilities interfering with an individual's social and occupational functions. "The positive association between CTSB and cognition, and the modulation of lipid metabolites implicated in dementia, support the beneficial effects of exercise training on brain function." (PMID 34093436, 2021). "Overall, the positive correlation between CTSB and cognition, and the substantial modulation of lipid metabolites implicated in dementia, support the beneficial effects of aerobic exercise on brain health in asymptomatic individuals at risk for AD." (PMID 34093436, 2021). "Overall, our analyses indicate metabolic regulation of exercise-induced plasma BDNF changes and provide evidence that CTSB is a marker of cognitive changes in late middle-aged adults at risk for dementia." (PMID 34093436, 2021). "In contrast, low levels of cathepsin B were seen in the hippocampus of an HIV-1 positive individual with HIV-associated dementia (HAD), and higher levels in an individual with mild cognitive motor disorder (MCMD)." (PMID 22693552, 2012). "Lower CTSB levels were also significantly associated with higher risk of dementia (2SMR)." (PMID 41266628, 2025). "Their findings suggest that exercise-induced changes in plasma brain-derived neurotrophic factor and CTSB may enhance cognitive function in adults at risk for dementia." (PMID 39221402, 2024). "In addition, the CTSB gene was identified as a PD risk allele, and elevated CtsB activity was recently reported in dementia with LBs (DLB), another synucleinopathy." (PMID 31092553, 2019). "The positive relationship between CTSB and cognitive performance, along with the modulation of lipid metabolites, underscores the beneficial effects of exercise on brain function, positioning CTSB as a potential marker for cognitive changes in middle-aged adults at risk for dementia." (PMID 39935805, 2024). "In other dementia types, such as PD, the cathepsin B rule is controversy, but it is believed that the enzyme is important for protein clearance, so its inhibition would be prejudicial for the patients." (PMID 36286438, 2022). "As mentioned in the Results section, this second cluster includes genes that have also been related to other dementia types (e.g., GRN, TMEM107B, SNX1, MAPT, CTSB and CTSH)." (PMID 36066633, 2022).
lymph node metastasis (9 papers, 2011 to 2026). "Kim verified overexpression of CTSB in tumor samples and identified its association with increased risk of lymph node metastasis." (PMID 35872750, 2022). "Further studies to validate CTSB as a prognostic marker in IBC and delineate the mechanisms by which the association of CTSB with cav-1 is involved in lymph node metastasis in IBC patients are in progress." (PMID 21199580, 2011). "Analysis of Cathepsin B in saliva revealed a significant correlation with histopathological grade and the presence of lymph node metastasis, making it a potential biomarker for non-invasive OSCC monitoring." (PMID 40818120, 2026). "Since we found that expression of CTSB was significantly correlated with the presence of lymph node metastasis, the effects of the CTSB knockdown on the oral cancer cell line were investigated by cell transwell migration assay." (PMID 27031837, 2016). "Higher CTSB expression was detected in patients with lymph node metastasis and poorly differentiated tumors." (PMID 27031837, 2016). "Further analysis showed that the upregulation of CTSB or CTSD was significantly correlated with lymph node metastasis, advanced clinical stage, recurrence, distant metastasis, and poor prognosis." (PMID 26995190, 2016). "Thus, our data demonstrate that CTSB may be a potential prognostic marker for lymph node metastasis in IBC." (PMID 21199580, 2011). "Cathepsin B, a protease involved in tumor invasion and metastasis, was significantly elevated in the saliva of OSCC patients, particularly those with high tumor grade and lymph node metastasis." (PMID 40818120, 2026). "We conclude that CTSB expression may be useful for determining OSCC prognosis, particularly for patients with lymph node metastasis, and may function as a biomarker of the survival of OSCC patients in Taiwan." (PMID 27031837, 2016). "Correlation between lymph node metastasis and expression of CTSB and cav-1 in IBC versus non-IBC patients." (PMID 21199580, 2011).
oral cancer (9 papers, 2010 to 2024). "It is considered a promising biomarker as increased expression of Cathepsin B was reported in various types of metastasis and invasive cancers such as lung, breast, ovary, colon, gastric, nasopharyngeal and oral cancer." (PMID 35260133, 2022). "Univariate and multivariate analysis of Cathepsin B and clinicopathological parameters among patients with oral cancer using the Cox proportional hazard regression model." (PMID 27031837, 2016). "For instance, cathepsin B mediates apoptosis induced by TRAIL in oral cancer cells and necrosis induced by nigericin in THP-1 cells." (PMID 21092200, 2010). "In addition, a most recent study reported that NCS suppressed oral cancer metastasis by modulating cathepsin B and extracellular signal-related kinase pathways." (PMID 37640882, 2023). "Increased expression of Cathepsin B was observed in many malignancies including oral cancer." (PMID 35260133, 2022). "In addition, the metastatic effects of the CTSB knockdown on two oral cancer cell lines were investigated by transwell migration assay." (PMID 27031837, 2016). "In oral cancer cells, cathepsin B has been shown to mediate TNFSF10-induced apoptosis." (PMID 25050621, 2014). "Moreover, treatment with the CTSB siRNA exerted an inhibitory effect on migration in OC2 and CAL27 oral cancer cells." (PMID 27031837, 2016). "Cytoplasmic CTSB expression in oral cancer was examined using immunohistochemistry, and patients were divided into two groups on the basis of CTSB staining: overall negative and positive (1+/2+)." (PMID 27031837, 2016).
osteoporosis (9 papers, 2011 to 2023). A condition of reduced bone mass, with decreased cortical thickness and a decrease in the number and size of the trabeculae of cancellous bone (but normal chemical composition), resulting in increased fracture incidence. "While inhibitors of cathepsin B and S are currently being evaluated in clinical trials, recent failure of Odanacatib, a cathepsin K inhibitor for osteoporosis, in late stage clinical trial has made pharmaceutical industries wary of targeting cathepsins." (PMID 32041276, 2020).
parasite infection (9 papers, 2013 to 2022). "Antigen-presenting cell expression of CTSB has been shown to downregulate Th1 cytokine responses in response to intracellular parasite infection." (PMID 34442377, 2021). "It is believed that the frustrated lysosome and associated cathepsin B release and activation are one of the important mechanisms mediating NLRP3 inflammasome activation during bacterial and parasite infections." (PMID 27322427, 2016).
bladder cancer (8 papers, 2015 to 2023). "Another study in bladder cancer demonstrated that active cathepsin B activated the AURKA/PI3K/AKT axis and promoted angiogenesis." (PMID 36973424, 2023). "Overall, our results show that apoptotic cell death induced by sorafenib in bladder cancer cells is dependent on cathepsin B activity and involved PTEN and Akt signaling pathways." (PMID 26097873, 2015). "According to Xinyuan Li, cathepsin B (CTSB) was upregulated in exosomes derived from serum of bladder cancer patients, directly ingesting EV-CTSB prominently activated TPX2-mediated phosphorylation of the AURKA-PI3K-AKT axis, increased VEGFA expression, finally promoted angiogenesis." (PMID 37805491, 2023).
Cerebral ischemia (8 papers, 2020 to 2024). Restriction of arterial blood supply to the brain associated with insufficient oxygenation to support the metabolic requirements of the tissue. "In comparison with the Sham group, cerebral ischemia caused a notable upregulation in the expression of Beclin-1, Cathepsin B, and MAPLC3β." (PMID 38397792, 2024). "The release of CTSB can induce changes in mitochondrial outer membrane permeability and result in cell death, ultimately contributing to cerebral ischemia–reperfusion injury." (PMID 39498393, 2024). "Sevoflurane postconditioning suppresses the activation and release of lysosomal cathepsin B and alleviates reactive astrogliosis and glial scar formation after cerebral ischemia-reperfusion." (PMID 32089771, 2020). "2-(3′,5′-Dimethoxybenzylidene) cyclopentanone (DMBC), a novel synthetic small-molecule compound, inhibits the release of cathepsin B from the lysosomes into the cytoplasm after cerebral ischemia, thereby protecting neurons against ischemic injury." (PMID 32089771, 2020). "Interestingly, studies that focus on the role of muscle-released CTSB in cerebral ischemia are sparse." (PMID 34108925, 2021). "In our present study, the enzymatic activities of CTSB and CTSD were also altered after OGD/R treatment, suggesting that TMEM175 deficiency exerts a negative effect on the hydrolytic function of lysosomes following cerebral ischemia with reperfusion." (PMID 32799888, 2020). "Moreover, considering the adverse role of overactive autophagy in the process of stroke, we found that muscimol decreased the expression levels of Beclin-1, Cathepsin B, and MAPLC3β in cerebral ischemic rats, which suggested that muscimol inhibited autophagy induced by cerebral ischemia." (PMID 38397792, 2024). "The roles of calpain, CTSB, and PARP in the nuclear translocation of AIF have been studied in the pathology of cerebral ischemia, and the activation of calpain and CTSB favors the release of AIF." (PMID 36552871, 2022). "Specifically, cerebral ischemia can result in the inactivation of NSF ATPase activity, initiating a cascade of events: extensive accumulation of Golgi fragments, transport vesicles, and late endosomes, disrupting the Golgi-endosome-lysosome pathway and releasing cathepsin B (CTSB)." (PMID 39498393, 2024). "In contrast, a negative role for brain-derived CTSB in cerebral ischemia has been established." (PMID 34108925, 2021).